CRP (C-reactive protein)
Diseases named in the same sentence as CRP in open-access papers (continued):
Sharing a sentence is not in itself a finding about the gene and the disease.
cardiovascular disease (continued). "Additionally, lactation is known to improve the subclinical vascular indices of cardiovascular disease, to promote lipid metabolism, and to reduce serum concentrations of C-reactive protein." (PMID 25025761, 2014). "Ample data from both clinical and experimental studies have shown that a high level of plasma CRP is a risk factor as well as marker for cardiovascular diseases, although some studies failed to prove the risk of CRP compared to other risk factors." (PMID 24872601, 2014). "Vitamin D might elicit protective effects against cardiovascular disease by decreasing the level of circulating high-sensitivity C-reactive protein (hs-CRP), an inflammatory marker." (PMID 24918698, 2014). "So, while our results confirm chronic systemic inflammation in both RA and IBD, we do observe a higher plasma level of CRP in RA, which may have some pathological impact on cardiovascular disease." (PMID 25337037, 2014). "Whereas initial experimental studies suggested a pathogenic role for CRP in atherogenesis, more recent genetic data from Mendelian randomization trials failed to provide evidence for a causative role of CRP in cardiovascular disease." (PMID 24799767, 2014). "The mechanism by which OSAS is associated with cardiovascular disease is not fully understood, but activation of the inflammatory cascade, potentially involving TNF-α, IL-6, or C-reactive protein (CRP), may be an underlying cause of these disease states." (PMID 24895539, 2014). "In conclusion, RA has a higher level of CRP and more pronounced traditional risk factors, compared to IBD, which may contribute to the different associations with cardiovascular disease and mortality reported." (PMID 25337037, 2014). "It is debated whether plasma levels of CRP and SAA are just passive bystanders of disease or whether these acute phase proteins are causally related to cardiovascular disease." (PMID 23894396, 2013). "A unique aspect of our study, in the assessment of causality with serum CRP, was the use of retinal vascular caliber (CRAE and CRVE), which are markers for systemic microvasculature and have been associated with subclinical and clinical cardiovascular disease." (PMID 23844046, 2013). "Whether there is a direct contribution of mildly elevated CRP levels to cardiovascular disease has been extensively debated." (PMID 24167754, 2013). "Biomarkers of the immune system, including serum levels of several inflammatory markers, such as C-reactive protein (CRP), fibrinogen, and interleukin 6 are independently associated with cardiovascular diseases (CVD) after adjustment for other known risk factors." (PMID 23977389, 2013). "CRP has emerged as the most promising cardiovascular event risk marker that may amplify the risk of T2DM and death from cardiovascular disorder, while TNF-α has served as a known mediator of IR." (PMID 23825680, 2013). "CRP, a biomarker of cardiovascular diseases, was highly related to MAGE in our study." (PMID 23936867, 2013). "Elevated CRP and IL-6 has been shown to predict development of cardiovascular disease." (PMID 23410093, 2013). "Circulating elevated levels of inflammatory markers, such as CRP, TNF-alpha, and IL-6, are associated with increased risk of developing cardiovascular disease; even some acute-phase reactants may also contribute to their pathogenesis." (PMID 23690772, 2013). "Extensive epidemiological studies of human CRP polymorphisms do not support the hypothesis that genetically determined elevated baseline levels of CRP contribute to human cardiovascular disease." (PMID 24167754, 2013). "As a vascular inflammatory marker, hs-CRP is closely related to cardiovascular disease." (PMID 24148690, 2013). "Since tHcy and CRP have demonstrated associations with cardiovascular disease and AD, we sought to investigate whether KIF6 719Arg carrier status is associated with tHcy and CRP in a group of clinically diagnosed AD and aMCI patients." (PMID 24455405, 2013).
cardiovascular disease (continued). "However, recent evidence suggested that CRP multimeric structure should be considered in addition to the CRP levels when investigating its pathological role and predictor value in cardiovascular disease and other diseases." (PMID 23516433, 2013). "We have investigated this notion in terms of both incident as well as recurrent cardiovascular disease (CVD) risk in population studies that have demonstrated high-risk for patients with concurrently high levels of HDL cholesterol (HDL-C) and C-reactive protein (CRP)." (PMID 23874812, 2013). "Investigations of whether CRP contributes mechanistically to cardiovascular disease have been extensive and controversial." (PMID 24167754, 2013). "Lower survival may also be associated with an ongoing inflammatory response, with elevated C-reactive protein, which is seen more often in males and which reflect an increased number of deaths from cardiovascular diseases mainly in men." (PMID 23861851, 2013). "Notably, CRP, a systemic inflammation marker, was reintroduced as a tool for monitoring malignancies, similar to its use in cardiovascular diseases in recent decades." (PMID 24255664, 2013). "If CRP is involved in the pathophysiology of cardiovascular disease, it could be expected that reducing the CRP level would prevent the development of cardiovascular complications." (PMID 22583484, 2012). "C-reactive protein (CRP), plasminogen-activator 1(PAI-1), and fibrinogen are acute-phase reactants, but among all of them, CRP in particular has been focus of attention because elevated levels constitute a risk factor for cardiovascular disease (CVD)." (PMID 22322513, 2012). "CRP is a sensitive marker of systemic low-grade inflammation and elevated plasma levels of CRP have been associated with an increased risk of coronary cardiovascular disease in individuals who have no prior cardiovascular disease." (PMID 23492862, 2012). "It was recently postulated that circulating antioxidants also have a role in the prevention of cardiovascular disease (CVD): C-reactive protein (CRP) and oxidized LDL-cholesterol concentrations, are inversely related to plasmatic concentrations of vitamin C, carotenoids and phenols." (PMID 22690145, 2012). "So, reducing the CRP levels can reduce mortality and morbidity due to cardiovascular disorders." (PMID 22524121, 2012). "Cardiovascular diseases are accompanied by the elevation of several positive acute phase reactants such as C-reactive protein (CRP), serum amyloid A (SAA), fibrinogen, white blood cell count, secretory nonpancreatic phospholipase 2-II (sPLA2-II), ferritin, and ceruloplasmin." (PMID 24049653, 2012). "Joint relationship between IL-6, D-dimer and hs-CRP, D-dimer with cardiovascular disease (CVD)." (PMID 22970224, 2012). "According to a meta-analysis of the Emerging Risk Factors Collaboration including 160,309 subjects CRP shows a positive association with risk of cardiovascular disease similar to non-high density lipoproteins or systolic blood pressure." (PMID 23029307, 2012). "Increased levels of CRP may reflect the severity of airway inflammation with a strong prognostic value, and CRP has recently become a therapeutic target in cardiovascular diseases." (PMID 22463705, 2012). "When compared to CRP, PTX3 predicted prevalent cardiovascular disease better, had fewer associations with other vascular risk conditions and may be more specific for vascular wall inflammation." (PMID 22319633, 2012). "Plasma CRP concentrations associate with cognitive performance in part through pathways independent of (risk factors for) cardiovascular disease." (PMID 21915265, 2011). "Elevated plasma CRP is a well-known marker of cardiovascular disease, which could imply that elevated CRP levels are associated with overall survival through the association with cardiovascular disease." (PMID 21639875, 2011). "CRP, as a systemic marker of inflammation, is a predictive marker for cardiovascular diseases." (PMID 23019501, 2011).
cardiovascular disease (continued). "In a review of inflammatory markers of cardiovascular diseases, Ramos and co-authors suggested that IL-6 and TNFα may be more useful than CRP in predicting cardiac risks among the elderly." (PMID 20653951, 2010). "This second hypothesis may be more compatible with the fact that the level of CRP increases during cardiovascular diseases." (PMID 22577421, 2010). "The association between APOE and CRP was not materially affected by adjustment for age, sex, history of cardiovascular disease, or cardiovascular risk factors." (PMID 20074603, 2010). "However, CRP is the marker of chronic inflammation most frequently studied and has been shown to predict cardiovascular diseases more than other cytokines." (PMID 20847810, 2010). "Although it is outside the scope of this review to detail all potential roles of IL-6 (or its downstream product, C-reactive protein (CRP)) as a cardiovascular biomarker in different cardiovascular diseases, it is important to emphasize that elevation of IL-6 is associated with diverse pathologies." (PMID 19936194, 2008). "In addition, several prospective studieshave demonstrated that plasma level of C-reactive protein (CRP) is an inflammatorymarker of cardiovascular disease." (PMID 19107216, 2008). "Beyond CRP’s ability to predict risk for both primary and secondary prevention of cardiovascular disease, interest has increased with the recognition that statins lower CRP in a manner largely independent of LDL-C reduction." (PMID 19690647, 2007). "In spite of the substantial observational data, application of D-dimer assays or other risk factor measurements such as for CRP have not gained acceptance in individual patients with PAD or other cardiovascular disease yet." (PMID 15574198, 2004). "We hypothesize that this association may stem from the following two factors: Firstly, as an inflammatory marker, elevated hs-CRP levels reflect heightened inflammatory responses in the body, which may further exacerbate renal damage and facilitate the progression of cardiovascular diseases." (PMID 40276550, 2025). "However, the present study focused on the relative associations (rather than the absolute values) of CRP with cardiovascular disease risk factors, and therefore the effect of different assays at the different time points is negligible." (PMID 40285470, 2025). "Furthermore, large-scale Mendelian randomization studies have demonstrated that genetically elevated CRP levels do not associate with increased cardiovascular disease risk, undermining the case for CRP (in either form) as a causal factor." (PMID 40943152, 2025). "However, of course, these encouraging studies supporting the important association of inflammation with incident cardiovascular disease need to be tempered by the prior understanding that CRP is not causally related to CHD." (PMID 40472800, 2025). "Future studies should explore the underlying mechanisms of CRP and lymphocyte fluctuations in CAD, evaluate their potential as therapeutic targets, and develop tailored intervention strategies to enhance the prevention and management of cardiovascular diseases." (PMID 39323757, 2024). "In addition, our results showed a negative correlation between salivary CRP and adiponectin levels, supporting their potential use as risk indicators of cardiovascular disease, which is consistent with previous research." (PMID 38433948, 2024). "The outcome measurements were cardiometabolic indices and risk factors for metabolic and cardiovascular diseases, including anthropometric index (body weight, BMI, WC), BP, lipid profile (TG, TC, HDL, LDL), glycemic markers (FBG, Hb1AC, Insulin), and inflammatory markers (CRP, IL-6, TNF-α)." (PMID 39285289, 2024). "Moreover, there were also study reported that platelet derived levels of CRP and IL-6 were associated with IFIT1 which may involve in cardiovascular disease risk factors." (PMID 38321374, 2024).
cardiovascular disease (continued). "Besides, in older age groups, the higher CRP may indicate a more severe general disease or even other inflammatory conditions such as auto-inflammatory conditions, cardiovascular disease, or active neoplasia." (PMID 39575025, 2024). "The exact method by which CRP contributes to cardiovascular disease is unknown." (PMID 37568846, 2023). "MR has also indicated no causal effect of high-density lipoproteins and C-reactive protein on cardiovascular disease, which, had it been reported earlier, could have saved a lot of effort and the cost of developing failed drugs." (PMID 35057415, 2022). "Path analysis adjusted for health‐related variables including depressive symptoms, cardiovascular disease, BMI, smoking, alcohol consume, and drug intake showed a significant direct effect of sleep disturbance to positive affect; positive affect directly predicted hs‐CRP." (PMID 35137495, 2022). "C-reactive protein (CRP) is a non-specific biomarker of inflammation and may be associated with cardiovascular disease." (PMID 35049659, 2022). "Whereas the molecule’s role as a marker of activity of infectious, autoimmune, ischemic or even cardiovascular disease is well established and generally accepted, it is important to note that there is no international consensus on causal contribution of CRP to the pathogenesis of any human disease." (PMID 35407379, 2022). "As pCRP and mCRP are now known to have distinctive anti- and pro-inflammatory bioactivities, respectively, it is possible to reassess the role(s) CRP may play in different lipoprotein-involved pathophysiologies such as cardiovascular diseases and neurodegenerative diseases." (PMID 36158829, 2022). "There is emerging evidence that the systemic inflammatory processes of IBD may contribute to the pathogenesis of cardiovascular diseases through increasing inflammatory mediators such as reactive oxygen species, C-reactive protein (CRP), and pro-inflammatory cytokines." (PMID 35955886, 2022). "However, it is believed that CRP may also be a potent marker for the detection of cardiovascular diseases." (PMID 35535358, 2022). "Similar to other cardiovascular diseases, this association was independent of the effects of CRP." (PMID 34168680, 2021). "CRP is also reported to be associated with LV T1 mapping indices in patients with systemic inflammation involving the heart or general population without known cardiovascular disease." (PMID 33745456, 2021). "In addition, cardiovascular diseases can also be monitored through CRP." (PMID 32781561, 2020). "Furthermore, in these disease states, GlycA is associated with cardiovascular disease (CVD) independent of traditional risk factors including C-reactive protein (CRP)." (PMID 34327480, 2020). "Our study included only women with normal serum levels of lipids and fasting glucose and women with no family history of cardiovascular diseases because abnormalities in these biochemical parameters and a family history of cardiovascular diseases may impact the plasma levels of CRP and AMH." (PMID 33198782, 2020). "Therefore, CRP inhibition could represent a viable new approach to prevent and treat of cardiovascular diseases." (PMID 32358950, 2020). "Because elevated circulating C-reactive protein (CRP) and low socio-economic status (SES), have both been implicated in cardiovascular disease development, we investigated whether SES factors associate with and interact with CRP polymorphisms in relation to the phenotype." (PMID 32933066, 2020). "As both inflammation markers, SF and CRP, also predict adverse cardiovascular events, we recommend intervention studies that achieve high 25(OH)D concentrations to establish their combined benefits in terms of preventing cardiovascular disease among obese subjects." (PMID 30909597, 2019).
cardiovascular disease (continued). "Concordantly, studies have shown the association of inflammatory markers especially CRP which is among the GPS score variables, interleukin-6 (IL-6), tumor necrosis factor alpha, pentraxin 3 and neutrophil-to-lymphocyte ratio with poor prognosis in cardiovascular diseases." (PMID 31096693, 2019). "Experimental studies involving short-term sleep deprivation in healthy individuals suggest that sleep disturbance leads to acute changes in inflammatory (including TNF-α, IL-6, CRP), metabolic, and other responses that could contribute to cardiovascular disease processes." (PMID 31287027, 2019). "Thus, GDF15 is produced by multiple cardiovascular cell types under stressful conditions so its correlation with the well-validated cardiovascular disease risk biomarker CRP is not surprising." (PMID 29967567, 2018). "Furthermore, we have reported that CRP may contribute to cardiovascular disease by also increasing oxidative stress and DNA damage." (PMID 29967567, 2018). "The authors aimed to prove that their sensor could be used to detect concentration changes with a resolution of about 1 μg/mL for the prevention of cardiovascular diseases; nevertheless, this sensor seems promising to detect the CRP concentration for monitoring wound healing." (PMID 29257113, 2017). "For inflammatory and hemostatic biomarkers, genetic studies suggest that IL-6 (a pro-inflammatory cytokine) and several coagulation factors are causal for cardiovascular disease, but such studies do not support a causal role for C-reactive protein and fibrinogen." (PMID 28477314, 2017). "Therefore, CRP could function as an inflammatory marker and mediated the function of lipid protein in obese and cardiovascular disease." (PMID 28115972, 2017). "Cardiovascular disease and VTE are closely linked conditions, share common risk factors, and may have common pathophysiological mechanisms; the current findings suggest that CRP may also play a role in the development of VTE." (PMID 28718029, 2017). "CRP did not change in most studies despite the use of highly-sensitive CRP kits, which are demanded for subjects with cardiovascular risk or established cardiovascular diseases." (PMID 27240397, 2016). "Finally, we evaluated whether low-dose acetylsalicylic acid, which is frequently prescribed to seniors for the prevention of cardiovascular disease, affects IL-6 and CRP concentrations." (PMID 27274758, 2016). "However, as CRP is a not a specific biomarker its use is limited in patients with other diseases in which CRP might be elevated, e.g. inflammatory or cardiovascular disease." (PMID 23497335, 2013). "Increased CRP levels without intima-media carotid artery thickening may suggest a possible role as a risk marker of cardiovascular disease and a mediator in atherogenesis due to its effects in endothelial cells as previously reported." (PMID 22701780, 2012). "Furthermore, C-reactive protein, a marker of inflammation and cardiovascular disease risk, was lowered regardless of dietary approach." (PMID 22925169, 2012). "Another limitation associated with using CRP as a predictor of mortality is that very high values of CRP may represent acute infection or injury not necessarily associated with cardiovascular disease." (PMID 21379581, 2011). "BMI = body mass index, CTI = C-reactive protein–triglyceride–glucose index, CVD = cardiovascular disease, NHANES = National Health and Nutrition Examination Survey." (PMID 40988175, 2025). "This activation correlates with elevated circulatory CRP and TNF levels, and the metabolic activity of the spleen independently predicted subsequent cardiovascular disease events." (PMID 40654268, 2025). "The C-reactive protein to albumin ratio (CAR) serves as a pivotal biomarker, demonstrating a strong correlation with adverse outcomes in cardiovascular disease (CVD)." (PMID 40128977, 2025).